EPHA2 (EPH receptor A2)
Diseases named in the same sentence as EPHA2 in open-access papers (continued):
Sharing a sentence is not in itself a finding about the gene and the disease.
glioma (continued). "U251 and C6 glioma cells, which expressed high levels of EphA2, could develop VM networks when cultured in Matrigel for 24 h and the VM network showed a positive reaction with periodic acid-Shiff (PAS)." (PMID 21264258, 2011). "This study demonstrated that miR-26b may act as a tumor suppressor in glioma and it directly regulates EphA2 expression." (PMID 21264258, 2011). "Indeed, we found that expression of EphA2 was significantly enhanced with the advance of glioma grade(p<0.01), accompanying the decrease of miR-26b." (PMID 21264258, 2011). "The growth ability of glioma cells in U87 MG, U251, and C6 cells transfected with 26b-DP was reduced with inhibition rates of 10.11%, 34.28% and 29.54%, respectively, suggesting that the inhibition rates of 26b-DP transfectants were related to endogenous EphA2 levels in glioma cells." (PMID 21264258, 2011). "In addition, TanCAR-redirected T cells targeting IL-13Rα2 or EphA2 in a xenograft mouse model, after subcutaneous injection of U87 glioma cells, were able to elicit greater tumor regression than single CAR-T cells with the potential for reduction of antigen escape and off-target cytotoxicity." (PMID 37443804, 2023). "Recently, glioma-specific antigens assessed in preclinical studies have shown potential anti-glioma effects, such as epidermal growth factor receptor variant III (EGFRvIII), human epidermal growth factor receptor 2 (HER2), and erythropoietin-producing hepatocellular carcinoma A2 (EphA2)." (PMID 36768267, 2023). "Therefore, EphA2 may be a specific tumor marker of glioma and is considered an important factor in glioma development." (PMID 35448036, 2022). "Our study showed that celastrol obviously reduced the numbers of VM channels and EVs and the expression of CD31, VEGFR2, Ang2, VEGFA, EphA2, and VE-cadherin in glioma xenograft tissues, indicating that celastrol might suppress tumor growth by inhibiting angiogenesis and VM formation in glioma." (PMID 32116702, 2020). "Additionally, survival analysis revealed that patients with high EphA2 levels had lower survival rates than those with low EphA2 levels, indicating that EphA2 may promote glioma progression." (PMID 32116702, 2020). "In addition, treatment with these EphA2-specific T cells suppressed EphA2-positive U373 glioma xenografts in severe combined immunodeficiency (SCID) mice and markedly increased animal survival in comparison with non-treated mice and those administered non-transduced T cells." (PMID 32811512, 2020). "EphA2 has been long recognized as a potential therapeutic target, being overexpressed in a range of cancer types, including both mesenchymal tumors such as melanoma and glioma, and epithelial tumors including prostate, breast, ovarian, lung, colon, esophageal, gastric, cervical, and bladder cancers." (PMID 32397088, 2020). "Consistent with NS-culture-derived glioma cells with high invasiveness, genes highly expressed in 51A were those encoding markers of neural stem/precursor cells (NANOG, POU3F2, POU5F1, and SALL2), and pro-invasive proteins (AGAP2, EPHA2, FOXM1, PDGFRA, and TNC)." (PMID 29113349, 2017). "In glioma, miR-26b directly reduces EphA2 expression and may act as a tumor suppressor." (PMID 26204489, 2015). "The glioma-specific antigens used in recent preclinical or clinical studies showing potent antiglioma effect include IL-13Rα2, human epidermal growth factor receptor 2 (HER2), epidermal growth factor receptor variant III (EGFRvIII), and erythropoietin-producing hepatocellular carcinoma A2 (EphA2)." (PMID 25009822, 2014). "EphA2 is overexpressed in roughly 90% of GBM cases and is significantly elevated compared to normal brain tissue and lower-grade gliomas." (PMID 41200151, 2025). "A mathematical model analyzing the expression hierarchy of three validated glioma antigens (HER2, IL13Rα2, and EphA2) predicted an increased likelihood of tumor elimination when any two of these three antigens are targeted." (PMID 40092990, 2025).
glioma (continued). "We next sought to investigate the cytotoxic potential of our mRNA-based single-targeting (HER2 CAR, IL13Rα2 CAR, or EphA2 CAR) and multi-targeting (CARPool#2 and MVCAR#2) CAR T cells against patient-derived glioma cells." (PMID 40896578, 2025). "Activated EphA2 was then shown to activate the PI3K pathway, which promoted the VM formation, migration, and proliferation of glioma cells." (PMID 40869298, 2025). "MRI features such as peritumoral edema, contrast enhancement, and tumor size also correlated with EphA2 and MMP-2 expression, reinforcing their role in glioma invasiveness." (PMID 41200151, 2025). "Specifically, the observation that a high expression of EPHA2 in neuroblastoma, EPHB1 in glioma, EPHB6, ephrin-B2, and ephrin-B3 in neuroblastoma correlates with a better prognosis is in line with a tumor-suppressive role of these EPHs." (PMID 38612645, 2024). "On the other hand, high expression levels of EPHA2 in neuroblastoma, of EPHB1 in glioma, and of EPHB6, ephrin-B2 and ephrin-B3 in neuroblastoma confer a better prognosis." (PMID 38612645, 2024). "Some members, such as EPHA2 and EPHA7, are overexpressed in glioma stem cells, indicating a poor prognosis." (PMID 38612645, 2024). "GAA Interleukin-13 receptor α2 (IL13Rα2), Ephrin type-A receptor 2 (EphA2), Wilms’ tumor gene 1 (WT1), and survivin were chosen as they are expressed in both high- and low-grade gliomas." (PMID 37509387, 2023). "It has been known that EFNA1 is a major cognate ligand of EPHA2 in vivo, but the function of EFNA1 is thought to impair EPHA2 activity in glioma cells, which promoted us to investigate the difference of PDGFA/EPHA2 axis and EFNA1/EPHA2 axis." (PMID 35105853, 2022). "Overexpression of ephrin-A1 downregulates EphA2 and FAK, leading to reduced migration, adhesion, and proliferation of glioma cells." (PMID 35448036, 2022). "Several glioma specific epitopes such as IL13RA2 and EphA2 are under investigation for poly-target therapy with antibody drug conjugates (ADCs) and CAR-T cells." (PMID 33435537, 2021). "The EphA2-specific T cells were subsequently improved via CH2CH3 spacer replacement with an IgG1-derived short spacer, increasing the anti-glioma effects of CD28.ζ CAR T cells by 20-fold." (PMID 32811512, 2020). "On molecular level, EphA2 has been shown to drive proliferation and invasion in multiple tumor forms including NSCLC, prostate cancer, and glioma." (PMID 27533087, 2016). "The putative roles for VE-cadherin and EphA2 in regulating the glioma microenvironment are discussed in further detail below (section The VE-cadherin (CDH5) and EphA2 pathways)." (PMID 26085929, 2015). "T cells and expressing CARs for the glioma-specific antigens including IL-13Rα2, HER2, EGFRvIII, and EphA2 show potent antiglioma activity in preclinical animal studies." (PMID 25009822, 2014). "Doxazosin directly bound to the recombinant EphA2 LBD with μM affinity and induced phosphorylation of EphA2 at similar doses in breast and prostate cancer cells, as well as glioma and hepatoma cells." (PMID 22916121, 2012). "Hypoxic glioma cell lines increased their mRNA expression for nine TAPP (Aim2, Art-4, EphA2, EZH2, Fosl1, PTH-rP, Sox 11, Whsc2 and YKL-40), as assessed by quantitative reverse transcriptase real-time/polymerase chain reaction (qRT-PCR)." (PMID 22957023, 2012). "However, the expression of EPH receptor A2 (EphA2), a potential indicator of VM formation, was not remarkably regulated after overexpressing L1 in glioma cells, suggesting that the EphA2 signal might not be associated with L1‐mediated VM formation in glioma." (PMID 36708044, 2023). "In particular, EphA2 is not expressed in normal brain tissue but is highly expressed in more than 90% of gliomas." (PMID 35448036, 2022). "This approach has yielded fruitful results in preclinical glioma models, as shown by the development of tandem CAR T cells that bind HER2 and IL13Rα2, as well as trivalent CAR T cells targeting HER2, IL13Rα2 and EphA2." (PMID 34298615, 2021).
glioma (continued). "In a U251-MG glioma cell line, the expression of EGFRvIII may result in specific up-regulation of some genes (TGF-α, EPHA2, HB-EGF, IL8, FOSL1, MAP4K4, DUSP6, and EMP1) influencing signaling pathways involved in oncogenesis." (PMID 33435537, 2021). "A luciferase reporter assay indicated that EphA2 serves as a miR-141′s target in glioma cells, and that there is a negative correlation between miR-141 and the expression of EphA2." (PMID 32169087, 2020). "The decreased proteins include proteins with known functions for glioma stemness and migration/invasion like CD9 (Gos, ATO/Gos), Ephrin receptor A2 (EPHA2; Gos, GANT/Gos) and mesenchymal (i.e., more aggressive) differentiation like FRAS1 related extracellular matrix protein 2 (FREM2; ATO/Gos)." (PMID 30871073, 2019). "Our proteomic data suggested the disturbance of processes related to cell movement, highlighted by decreased levels of several proteins involved in glioma migration, such as CD9 and EPHB3 after treatment with Gos or ATO/Gos, as well as EPHA2 after treatment with GANT/Gos." (PMID 30871073, 2019). "EphA2 is also highly expressed in various types of GBM cell lines, including U87-MG, DBTRG-05M, U251MG, BTCOE 4795, LN229, and T98G, as well as in human glioma stem cells (GSC), including D456MG, 827, and 1228 cells." (PMID 30914876, 2018). "In addition, infiltrative invasion of glioma stem cells expressing EphA2 in vivo, which is completely independent of ephrin-A1, A3 and A4 ligands, was disrupted by S897A mutation." (PMID 26158630, 2015). "In this study we provided evidence that ephrinA5-Fc stimulation induces increased expression of EphA2 in DAOY cells, suggesting that Eph receptor activation by cognate ligands, e.g., presented by the microenvironment, could trigger the overexpression observed in glioma." (PMID 33572758, 2021).
glioblastoma (92 papers, 2008 to 2025). The most malignant astrocytic tumor (WHO grade IV). "Higher EphA2 and EphA8 expression were associated with poorer, while higher EphA3 expression was associated with better, prognosis in patients with glioblastoma, respectively." (PMID 37146061, 2023). "For instance, high expression of EphA2 and EphA3 has been linked to poor survival identified in glioblastoma multiforme (GBM)." (PMID 35215250, 2022). "EphA2 is a tumor-associated-antigen overexpressed in glioblastoma." (PMID 34235085, 2021). "Similarly, EphA2 might also be linked to GBM (glioblastoma) as a regulator of tumorigenesis, invasion, metastasis, and angiogenesis." (PMID 39942820, 2025). "Examples include [64Cu]DOTA-1C1 mAb, which binds both human and mouse EphA2 and has been used for noninvasive PET imaging of EphA2 in colorectal, melanoma, glioblastoma, and ovarian cancers." (PMID 40225586, 2025). "Conversely, a large number of glioblastoma tumor cells express ephrin type A receptor 2 (EphA2) and interleukin 13 receptor α2 (IL13Rα2)." (PMID 40308611, 2025). "For instance, [64Cu]DOTA-1C1 mAb, which binds both human and mouse orthologs, was used for noninvasive PET imaging of EphA2 levels in various tumor types, including colorectal cancer, melanoma, glioblastoma, and ovarian cancer." (PMID 40225586, 2025). "Compound 51 effectively inhibited the EphA2–ephrin-A1 interaction and suppressed EphA2 phosphorylation in U251 glioblastoma cells at concentrations of 30 μM." (PMID 39407697, 2024). "In a recent study, the authors used two different sets of CARs targeting different epitopes of EphA2 and tested in vitro and in vivo efficacy in glioblastoma." (PMID 39596256, 2024). "engineered the first T cells secreting BiTEs that were designed to enable a targeted immune response against the ephrin type-A receptor 2 (EphA2), which is expressed on glioblastoma, breast, prostate, and lung tumor cells." (PMID 39711794, 2024). "Another clinical trial was conducted, recruiting patients with recurrent EphA2-positive glioblastoma treated with EphA2-CAR-T cells (NCT03423992)." (PMID 39596256, 2024). "Taken together, we propose EphA2 as a crucial cell factor for HCMV infection in glioblastoma cells and a potential target for intervention." (PMID 37146061, 2023). "We identified EphA2 as a host factor for HCMV infection of human glioblastoma cells by siRNA screen." (PMID 37146061, 2023). "A first-in-human trial of EphA2-redirected CAR-T cells was performed in three patients with recurrent glioblastoma." (PMID 37443804, 2023). "The results revealed that EphA2, EphB2, EphB3, and EphB4 were significantly upregulated, while EphA4 and EphB6 were significantly downregulated in glioblastoma than normal brain tissues, respectively." (PMID 37146061, 2023). "EphA2 is often overexpressed in various cancer cells, including breast cancer, lung cancer, and glioblastoma multiforme." (PMID 37059179, 2023). "A clinical trial had been initiated to examine the efficacy of EphA2-CAR T cells on glioblastoma patients but has been discontinued." (PMID 36721153, 2023). "It has been revealed that glioblastoma cells overexpress the erythropoietin-producing hepatocellular carcinoma A2 (EphA2) that plays an essential role in carcinogenesis and cell migration." (PMID 36721153, 2023). "We stably overexpressed the wild-type EphA2 (EphA2wt)or EphA2Δcyto in glioblastoma T98G cells, which were then infected with HCMV." (PMID 37146061, 2023). "EphA2-derived epitopes can induce the elevated immunoreactivity of CD4+ and CD8+ T cells in the EphA2-positive renal cell carcinoma, and dendritic cell vaccination with EphA2 peptides has been applied in the clinical trial of glioblastoma multiforme." (PMID 37637034, 2023). "Here, we show that EphA2 was upregulated in glioblastoma and correlated with the poor prognosis of the patients." (PMID 37146061, 2023). "EphA2, known for its overexpression in glioblastoma, plays a role in enhanced tumorigenesis and metastasis." (PMID 38067356, 2023).
glioblastoma (continued). "Trispecific CAR T cells that target HER2, IL13Ra2, and EphA2 offer more thorough coverage of tumor antigens and have been demonstrated to considerably extend the longevity of mice, bearing glioblastoma patient-derived xenografts." (PMID 36721153, 2023). "EphA2 silencing inhibits, whereas overexpression promotes HCMV infection, establishing EphA2 as a crucial cell factor for HCMV infection of glioblastoma cells." (PMID 37146061, 2023). "Other markers noted in studies that identified VM-capable glioblastoma cells were expression of VE-cadherin, MMP-2, MMP-9, and EphA2, all of which have previously been associated with VM in melanoma." (PMID 36823554, 2023). "By siRNA screen of Eph receptors family members, combined with a series of loss-of-function, gain-of-function, and protein-protein interaction assays, we identified EphA2 as an entry co-receptor for HCMV infection of glioblastoma." (PMID 37146061, 2023). "In vitro, EphA2 targeting CAR T cells effectively eliminates differentiated glioblastoma cells and glioblastoma cancer stem-like cells, significantly prolonging the survival of orthotopic xenograft mice." (PMID 36721153, 2023). "The increased expression of ephrin receptor A2 (EphA2) and ephrin receptor A3 (EphA3) correlated with poor prognosis in patients with glioblastomas." (PMID 37146061, 2023). "Altogether, these results suggested that blocking EphA2 impairs HCMV infection of glioblastoma cells and highlighted EphA2 as a potential therapeutic target to halt HCMV infection in glioblastoma cells." (PMID 37146061, 2023). "A novel TanCAR T cell designed to target both IL13 Ra2 and EphA2 can effectively recognize and eliminate glioblastoma tumor cells when encountering IL13Ra2 or EphA2 alone, as well as both targets simultaneously." (PMID 38067356, 2023). "Other antigens tested in glioblastoma models, most of which have already made it into clinical testing as below, include EphA2, B7-H3, CD133, CD70, GD2, NKG2D, Fn14, and podoplanin." (PMID 37754534, 2023). "Tri-specific CAR T-cells targeting HER2, IL13Ra2, and EphA2 achieve a wider coverage of antigens, and studies have shown that this strategy prolongs the survival of mice bearing glioblastoma patient-derived xenografts." (PMID 35692797, 2022). "In glioblastoma and prostate cancer cell lines, overexpression of EPHA2 resulted in oncogenic signals." (PMID 35008410, 2022). "It inhibits the viability of EphA2 growth dependent glioblastoma cells with a half-maximal effective concentration (EC50) of 5 μm." (PMID 35359869, 2022). "Glioblastoma-derived cells in vitro demonstrated expression of IL13Rα2, EphA2 and Fra-1, described previously as AAAs (astrocytoma-associated antigens) facilitating tumor culture establishment." (PMID 33245508, 2022). "Overexpression of EphA2 was also observed in human glioblastoma multiform (GBM) tumors, even accounting as a novel molecular marker and target in GBM." (PMID 33572758, 2021). "We conduct the first-in-human trial of EphA2-redirected CAR T-cells in patients with EphA2-positive recurrent glioblastoma and report the results of three patients enrolled as the first cohort receiving the starting dosage (1×106 cells/kg)." (PMID 34235085, 2021). "Of note, ephrinA5 stimulation caused an increased expression of EphA2 in DAOY cells, which is interesting as EphA2 overexpression was observed in numerous cancer cells including human glioblastoma multiform (GBM) tumors." (PMID 33572758, 2021). "Based on these, we conducted a single-arm, dose-escalation, first-in-human pilot trial of EphA2-redirected CAR T-cells in patients with recurrent EphA2-positive glioblastoma." (PMID 34235085, 2021). "In contrast, various types of tumor cells including glioblastoma up-regulated EphA2 expression, which makes EphA2 an attractive target for immunotherapy." (PMID 34235085, 2021). "Pre-clinical studies have demonstrated the promise of EphA2-redirected CAR T-cells against glioblastoma." (PMID 34235085, 2021).